RAB11B (RAB11B, member RAS oncogene family)
Diseases named in the same sentence as RAB11B in open-access papers:
RAB11B is named in the same sentence as 32 diseases in open-access papers, as found by Europe PMC text mining. Sharing a sentence is not in itself a finding about the gene and the disease. The quoted sentences say what the papers report.
breast carcinoma (4 papers, 2018 to 2023). "Lipophilic statins prevent membrane association and activity of Rab11b, and we provide proof-of principle that these drugs prevent breast cancer adaptation to the brain microenvironment." (PMID 32541798, 2020). "To determine whether Rab11b plays a causal role in breast cancer brain metastasis formation, we used two shRNA constructs targeting Rab11b and confirmed that they decrease Rab11b mRNA and protein, as well as active Rab11b." (PMID 32541798, 2020). "Taken together, these data demonstrate that Rab11b enhances brain metastasis formation following lodging in the brain parenchyma through specific interactions with the brain microenvironment, and loss of Rab11b is sufficient to decrease breast cancer brain metastasis." (PMID 32541798, 2020). "In a different cell type, BT20 breast cancer cells, knockdown of Rab4a, Rab4b, Rab11a, Rab11b or Rab25 significantly decreased motility, as did knockdown of CLINT1 or SH3BP5L." (PMID 37232246, 2023). "Taken together, these results suggest that breast cancer cells up-regulate Rab11b shortly after arriving in the brain metastatic microenvironment, and this up-regulation translates to increased Rab11b functional activity." (PMID 32541798, 2020). "Given the role of Rab11b in breast cancer brain metastasis, we sought to pharmacologically inhibit Rab11b." (PMID 32541798, 2020). "We find that breast cancer cells up-regulate Rab11b during early adaptation to the brain metastatic site, providing a mechanism for DTCs to recycle needed proteins during this critical step of the metastatic cascade, enabling survival and outgrowth." (PMID 32541798, 2020). "Together, these data suggest that Rab11b-mediated recycling of integrin β1 enhances the ability of breast cancer cells to successfully attach, activate attachment-mediated signaling, and ultimately survive in sub-optimal ECM conditions." (PMID 32541798, 2020). "Taken together, thse data show that pitavastatin and simvastatin are able to inhibit Rab11b activity, leading to decreased recycling of integrin β1, and ultimately suppressing the ability of breast cancer cells to successfully engage the brain metastatic ECM." (PMID 32541798, 2020). "We show that breast cancer cells significantly up-regulate Rab11b in the brain metastatic site compared to the primary site." (PMID 32541798, 2020). "Examination of breast cancer cells in culture reveals that knocking down Rab11b slightly decreases overall expression of integrin β1, but leads to dramatic loss of cell-surface integrin β1, suggesting a loss of localization." (PMID 32541798, 2020). "To determine if we can recapitulate the induction of Rab11b in vitro, we co-cultured breast cancer cells with primary murine glia, and found that only Rab11b is up-regulated." (PMID 32541798, 2020). "Although recycling-mediated localization of specific proteins has been individually studied before, our study demonstrates that, through control of a subset of proteins, Rab11b controls the cell-surface proteome to mediate breast cancer metastatic adaptation to the brain microenvironment." (PMID 32541798, 2020). "However, statin treatment significantly decreases the expression of integrin β1 in brain metastases, suggesting that statin treatment inhibits Rab11b-mediated recycling of integrin β1 to suppress breast cancer brain metastasis." (PMID 32541798, 2020). "In this study, we provide preclinical evidence, based on Rab11b-mediated metastatic adaptation, that repurposing statins could be a practical clinical strategy not only for breast cancer prevention, but also for brain metastasis prevention." (PMID 32541798, 2020). "To determine whether Rab11b directly impacts the ability of breast cancer cells to engage the brain ECM, we cultured tumor cells on decellularized murine brain ECM36." (PMID 32541798, 2020).
breast carcinoma (continued). "In addition to sensing the level of Rac activity in adjacent cells to organize individual cells in cell clusters, Rab11b is necessary for metastatic breast cancer cells to adapt to the brain microenvironment, since Rab11b manipulates the expression of critical proteins at the cancer cell surface." (PMID 36046433, 2021). "Further, brain metastases derived from multiple breast cancer cell lines showed more than 15 fold increase of Rab11b expression compared with cultured cells, with no change in Rab11a or Rab25 levels, suggesting the brain metastatic microenvironment specifically influences Rab11b expression." (PMID 32541798, 2020). "Thus, we postulate that through inhibition of the mevalonate pathway, statin treatment could also suppress Rab11b activation, which we have shown is an essential step for breast cancer adaptation to the brain metastatic microenvironment." (PMID 32541798, 2020).
Intellectual disability (3 papers, 2018 to 2023). "RAB11B has a pivotal role in vesicular trafficking, and mutations on this gene correlate with intellectual disability and microcephaly." (PMID 34880900, 2021). "Both Rab11A and Rab11B are mutated in developmental disorders, with putative inactivating Rab11A or Rab11B mutations leading to intellectual disability and brain malformation." (PMID 30217979, 2018). "Rab11A and Rab11B are mutated in developmental disorders, leading to encephalopathies and co-occurrence of seizures and intellectual disability." (PMID 30217979, 2018). "It is noteworthy that RAB11B and RAB11B-AS1 are downregulated by CDH8, and therefore, known CDH8 variants may modulate the cellular level of RAB11B, leading to macrocephaly and intellectual disability." (PMID 37408531, 2023).
COVID-19 (2 papers, 2022 to 2024). A disease caused by infection with severe acute respiratory syndrome coronavirus 2. "We proceeded with Mann Whitney U Test and found that RAB5 expression was significantly increased (P < 0.001), and RAB7 and RAB11B expression was significantly decreased (P < 0.001 and P = 0.036) in the COVID-19 patient group compared to the control group." (PMID 35840993, 2022). "We found the Median (inter-quartile range/IQR) of RAB5, RAB7, and RAB11B expression among the COVID-19 patient group was 2.99 (1.88), 0.17 (0.47), 0.47 (1.49), and 1.60 (2.88), 1.05 (2.49), 1.10 (3.96) among control group respectively." (PMID 35840993, 2022). "This study aims to compare the expression of RAB5, RAB7, and RAB11B between positive and negative COVID-19 patient groups." (PMID 35840993, 2022). "This first report showed significant differences in RAB5, RAB7, and RAB11B exist between COVID-19 positive and negative patients." (PMID 35840993, 2022). "If the data is distributed normally, the difference between RAB5, RAB7, and RAB11B from the COVID-19 positive and negative groups will be analysed using an independent t-test." (PMID 35840993, 2022). "Therefore, this study aims to compare the expression of RAB5, RAB7, and RAB11B between the COVID-19 positive and negative groups as categorized by the SARS CoV-2 ORF1ab and N-gene expression." (PMID 35840993, 2022). "Using Kolmogorov–Smirnov Test revealed that the distribution of RAB5, RAB7, and RAB11B expression was not normal, and the Mann–Whitney U test was performed to test the difference in the median value of RAB5, RAB7, and RAB11B between COVID-19 positive group and negative group." (PMID 35840993, 2022). "Finally, we conclude that RAB5 expression was significantly increased and RAB7 and RAB11B expression was significantly decreased in the COVID-19 positive group compared to the negative group." (PMID 35840993, 2022).
Atrophy (1 paper, 2022). Any weakening or degeneration, especially through lack of use. "More generally, genetic aberrations of many of the differentially methylated genes in our study, i.e., TRIO, NRXN2, SYN2, CACNA1E, DNM1 and RAB11B, have been associated with movement disorders, cognitive and visual impairments and brain abnormalities (e.g., atrophy, white matter apoplasia)." (PMID 35094644, 2022).
diabetes (1 paper, 2022). "In addition, another recycling endosome marker, Rab11B, showed a similar distribution within the islet; it also did not colocalize with glucagon but colocalized with insulin; this pattern remained unchanged in diabetes." (PMID 34923907, 2022). "In contrast, insulin showed a strong colocalization with Rab11A (PCC 0.63 ± 0.09) or Rab11B (PCC 0.61 ± 0.06), which significantly decreased (p < .001) following induction of diabetes (colocalization of insulin with Rab11A, PCC 0.35 ± 0.5, or Rab11B, PCC 0.38 ± 0.07)." (PMID 34923907, 2022).
E. coli infection (1 paper, 2016). "Lnc-ANKRD37-1, lnc-RAB11B-3, lnc-PTTG1-1 and lnc-BIRC3-1, the levels of which were significantly increased in response to meningitic E. coli infection, were differentially regulated by the stimulation of different cytokines." (PMID 27958323, 2016).
lung carcinoma (1 paper, 2024). "This study reveals that except Rab7a, five Rab proteins, Rab8a, Rab11b, Rab27a, Rab35, and Rab37, were highly expressed in the purified AP of lung cancer cells (CL1‐5‐Q89L) with a high secretory tendency (Q) (column 4 vs. column 3)." (PMID 38804615, 2024).
microcephaly (1 paper, 2021). A congenital or acquired developmental disorder in which the circumference of the head is smaller than normal for the person's age and sex. "Importantly, RAB11B de novo mutations were correlated with Intellectual Disability and microcephaly." (PMID 34880900, 2021).
microvillus inclusion disease (1 paper, 2015). Microvillus inclusion disease (MVID) is a very rare, severe, malabsorbative syndrome characterized clinically by protracted or intractable neonatal secretory diarrhea and histologically by inclusion bodies on the intestinal epithelium. "Mutations in MYO5B encoding Myosin 5b, which acts as a molecular motor not only for Rab11a, but also Rab11b, Rab25, and Rab8, cause MicroVillus Inclusion Disease (MVID) in which malabsorption results from the absence of the intestinal brush border." (PMID 26116792, 2015).
ovarian carcinoma (1 paper, 2022). A malignant neoplasm originating from the surface ovarian epithelium. "The main Rab11b protein-coding splice variant 201 is ~4× more abundant than the protein-coding splice variant 202, consistent with eQTLs analysis of ovarian cancer, and DExCon modification did not significantly influence their relative abundance." (PMID 35708998, 2022). "For further work, we selected a commonly used cell line model for ovarian cancer, A2780, and knocked-in mNeonGreen or mCherry after the start codon of Rab11a or Rab11b, respectively." (PMID 35708998, 2022). "To demonstrate the potency of our strategies on closely related genes, we deployed them to study members of the Rab11 family (Rab11a, Rab11b, and Rab25) in an ovarian cancer cell line that lacks endogenous Rab25 expression." (PMID 35708998, 2022). "FACS and fluorescence widefield images (background subtracted) of mNeonGreen or mCherry knock-ins to Rab11a or Rab11b loci of (D) A2780 or (E) COV362 ovarian cancer cell lines." (PMID 35708998, 2022). "Rab11a, Rab11b, and Rab25 were significantly enriched in ovarian cancer, both for primary and recurrent tumors." (PMID 35708998, 2022). "Similarly, several Rab11a/Rab11b/Rab25 splicing isoforms are enriched in ovarian cancer compared to normal tissue." (PMID 35708998, 2022). "Furthermore, our results suggest that although Rab11b and Rab11a may have a complementary function in migration and invasion of A2780 ovarian cancer cells, they differ substantially in their post-transcriptional regulation." (PMID 35708998, 2022).
pancreatic cancer (1 paper, 2019). "(A) Based on the GENT database, LASP1, RAB11B, RUVBL1 and MYO1B gene expression were analyzed in the pancreatic cancer tissues and normal pancreatic tissues." (PMID 31395079, 2019). "Based on the GENT database, we showed that both LASP1 and RUVBL1 gene expression were significantly upregulated in pancreatic cancer tissues compared with that in normal pancreatic tissues, while RAB11B was not changed obviously, and MYO1B was significantly downregulated." (PMID 31395079, 2019).
triple-negative breast carcinoma (1 paper, 2023). An invasive breast carcinoma which is negative for expression of estrogen receptor (ER), progesterone receptor (PR), and human epidermal growth factor receptor 2 (HER2). "We next sought to confirm our findings using BT20 triple-negative breast cancer cells, which express Rab4a, Rab4b, Rab11a, Rab11b and Rab25." (PMID 37232246, 2023).
tumor (34 papers, 2009 to 2025). "In this context, we assessed the clinical value of 8 genes (RAB2B, RAB3B, RAB9A, RAB11B, RAB27A, RAB27B, STX1A, and VAMP7), which are implicated in sEVs biogenesis, as well as their association with overall and tumor-derived plasma sEVs levels." (PMID 36980570, 2023). "We found that Rab11b is up-regulated in all three tissue microenvironments early in tumor or metastasis formation; however, Rab11b is significantly more strongly up-regulated during early brain metastasis formation (7 dpi)." (PMID 32541798, 2020). "We found that both statins successfully inhibited tumor cell growth in soft agar, phenocopying the effects of Rab11b knockdown." (PMID 32541798, 2020). "RAB11B is recognized as a functional mediator of metastatic adaptation, because it participates in the recycling of proteins such as integrin β1 necessary for the interaction of tumor cells with the microenvironment." (PMID 39494346, 2024). "In addition, high tumor expression of RAB27A, RAB27B, RAB9A, RAB11B, and STX1A was favorable of a 5-year survival (p = 0.038, p = 0.015, p = 0.008, p = 0.002, and p = 0.028, respectively)." (PMID 36980570, 2023). "Taken together, these data suggest that Rab11b-mediated recycling controls the cell-surface proteome, maintaining integrin β1 surface localization, where it can be activated by the ECM to facilitate tumor cell survival." (PMID 32541798, 2020). "Rab11b protein was over-expressed (∼8000-fold) in the tumor tissues, yet was almost absent in the healthy lung tissues in all tested samples." (PMID 29285267, 2017). "We confirmed these results via Western blotting analysis of tumor cells expressing AFAP1-AS1 siRNA, and found that RhoA, Rac2, Rab10, Rab11a, Rhogdi and Pfn1 were significantly upregulated, but RhoC, Rab11b and Lasp1 were significantly downregulated in NPC cell lines." (PMID 26246469, 2015). "Interestingly, RAB11B, a RAS superfamily member of small GTP-binding proteins, was the only tumor cell gene with significantly different expression between responders and nonresponders pretreatment, suggesting an absence of intrinsic tumor cell differences between patient groups at baseline." (PMID 34795254, 2021).
cancer (10 papers, 2015 to 2025). A tumor composed of atypical neoplastic, often pleomorphic cells that invade other tissues. "The Rab11 family (Rab11a, Rab11b, and Rab25) controls the return of internalized cargos to the plasma membrane, and Rab25 has been implicated in the aggressiveness of cancer by promoting invasive migration." (PMID 40614209, 2025). "The Rab11 family (Rab11a, Rab11b and Rab25) is associated with recycling endosomes, and only Rab25 was previously reported as being associated with cancer." (PMID 29285267, 2017). "For example, Rab11b regulates the recycling of integrin β1, which allows cancer cells to engage with the brain ECM efficiently to activate mechanotransduction signaling." (PMID 36046433, 2021). "In this study, we identify Rab11b-mediated endosomal recycling as a unique mechanism for cancer cell adaptation to a challenging brain metastatic microenvironment." (PMID 32541798, 2020). "Although we found that Rab11b is the specific isoform up-regulated during BCBM, it is likely that the specific combination of primary cancer type and metastatic microenvironment will dictate the regulation and content of the recycleome." (PMID 32541798, 2020).
infection (9 papers, 2018 to 2025). The state of being infected such as from the introduction of a foreign agent such as serum, vaccine, antigenic substance or organism. "Although cells deficient in Rab11B showed reduced amount of toxin in the infection media, they showed normal levels of vesicle carrier intermediates." (PMID 35579416, 2022). "Yersinia pestis targets organelle trafficking and recruits Rab4a early in infection and Rab11b late in infection to prevent phagosome maturation and inhibit acidification in the lumen." (PMID 37841276, 2023). "We selected Rab5b, Rab11b, Rab8b and Rab11FIP1 for further characterisation in response to a ΔsdhA infection." (PMID 32096265, 2020). "While recruitment of Rab4a was necessary to inhibit YCV acidification and lysosomal fusion early during infection, Rab11b appeared to contribute to later stages of YCV biogenesis." (PMID 29463656, 2018). "At both 2 and 24 h postinfection, intracellular TfR intensity and TfR-positive endosomes per cell were significantly lower in cells overexpressing Rab11b-EGFP, demonstrating that overexpression of Rab11b restored host cell recycling during infection." (PMID 29463656, 2018). "Furthermore, Y. pestis continued to colocalize with Rab11b-EGFP at a high frequency throughout the course of the infection." (PMID 29463656, 2018). "To validate the functional roles of key DEGs, we performed in vivo knockdown experiments for PPO2, RAB11B, LAMP1, and Dorsal during DIV1 infection, and double-stranded green fluorescent protein (dsGFP) was used as a control (each 30 individuals)." (PMID 40679295, 2025). "For instance, EspF recruits clathrin, AP2, early (Rab5a and EEA1) and recycling (Rab4a, Rab11a, Rab11b, FIP2, Myo5b) endocytic proteins to sites of infection." (PMID 31947656, 2020). "We show that type-III secreted components prompt the recruitment of clathrin (clathrin and AP2), early (Rab5a and EEA1) and recycling (Rab4a, Rab11a, Rab11b, FIP2, Myo5b) endocytic machineries to peripheral plasma membrane infection sites." (PMID 31242273, 2019). "We therefore investigated the T3SS dependence of the distribution of clathrin endocytic (CHC, AP2-α, Rab5a and EEA1) and recycling [Rab11a, Rab11b, Rab25, Myosin 5b (Myo5b)] components upon EPEC infection of polarized MDCK cells." (PMID 31242273, 2019). "Moreover, knockdown of PPO2, RAB11B, LAMP1, and Dorsal resulted in more severe hepatopancreatic damage post-DIV1 infection compared to the control group." (PMID 40679295, 2025). "Knockdown of Rab4a resulted in rapid killing of Y. pestis within 2 h of infection, while changes in bacterial survival in Rab11b siRNA-treated macrophages were not apparent until later." (PMID 29463656, 2018).
neurodegenerative disease (1 paper, 2024). A disorder of the central nervous system characterized by gradual and progressive loss of neural tissue and neurologic function. "In our study, we detected Rab11B, which is highly expressed in the brain and involved in recycling via the recycling endosome and implicated in several neurodegenerative diseases." (PMID 39251023, 2024).
RAB11B also shares sentences with these, for which no sentence is quoted: rectal cancer (5 papers); lymph node metastasis (3); adenocarcinoma (1); Ataxia (1); cholangitis (1); encephalopathies (1); epilepsy (1); esophageal cancer (1); lung adenocarcinoma (1); lung squamous cell carcinoma (1); metastatic disease (1); movement disorder (1); respiratory failure (1); signet ring cell carcinoma (1); squamous cell carcinoma (1); Visual impairment (1).